LGALS7 (galectin 7)
Diseases named in the same sentence as LGALS7 in open-access papers (continued):
Sharing a sentence is not in itself a finding about the gene and the disease.
gastric cancer (continued). "In this study, we first determined the differential expression of galectin-7 in gastric cancer cell lines and tissues from gastric cancer patients compared with matched normal tissue." (PMID 23985992, 2013). "Here, we demonstrated diminished expression of galectin-7 in malignant tissues relative to matched normal tissues in 70% of gastric cancer patients, and also detected DNA methylation of the galectin-7 gene in malignant tissues of other gastric cancer patients." (PMID 23985992, 2013). "Galectin-7 has emerged as a potential tumor suppressor in gastric cancer." (PMID 40710343, 2025). "Interestingly, lower galectin-7 expression was detected in patients with gastric cancer compared to controls and the expression levels were significantly associated with tumor grade, stage, and better survival of patients with gastric cancer." (PMID 36873388, 2023). "Consequently, overexpression of galectin-7 strongly reduced gastric cancer cell proliferation, migration, and invasion." (PMID 36873388, 2023). "Evidence showed that galectin-7 can be regulated by the DNA methylation-mediated epigenetic mechanism and might have a tumor suppression role in gastric cancer." (PMID 33233689, 2020). "Our results suggest that high galectin-7 gene expression might be a poor prognostic factor for gastric cancer patients." (PMID 33233689, 2020). "Although galectin-7 might play an important role in cancer progression, the evidence of galectin-7 in gastric cancer progression is limited." (PMID 33233689, 2020). "Our present results demonstrate that Tid1 knockdown might contribute to migration and invasion in gastric cancer cells via the galectin-7-MMP-9 axis." (PMID 33233689, 2020). "In this study, we investigated galectin-7 expression and its role in gastric cancer." (PMID 23985992, 2013). "In this study, we suggest that galectin-7 functions as a gastric cancer suppressor." (PMID 23985992, 2013). "Therefore, we aimed to elucidate the mechanism by which galectin-7 suppresses gastric cancer proliferation and invasion." (PMID 23985992, 2013). "To confirm whether down-regulation of galectin-7 in gastric cancer cell lines depends on promoter methylation, we treated nine gastric cancer cell lines with 5-aza-dC and quantitatively monitored the change in methylation status by the EpiTYPERTM assay." (PMID 23985992, 2013). "We next investigated the role of galectin-7 in the progression in gastric cancer cells." (PMID 23985992, 2013). "Moreover, the survival probability was higher in gastric cancer patients with high galectin-7 expression in normal tissues (p=0.0561) although this was not statistically significant, possibly due to the limited number of samples." (PMID 23985992, 2013). "Our data strongly indicate that galectin-7 is down-regulated during gastric cancer progression." (PMID 23985992, 2013). "Furthermore, using the Kaplan–Meier plotter online database, which is based on the GEO, EGA, and TCGA databases, we found that galectin-7 gene expression might be a poor prognosis factor in gastric cancer patients." (PMID 33233689, 2020). "In addition, the Tid1-galectin-7-MMP-9 axis might be associated with Tid1 knockdown–induced cell migration and invasion of gastric cancer cells." (PMID 33233689, 2020). "Therefore, we propose that the expression of galectin-7 is critically regulated by DNA hypermethylation and might play a role in gastric cancer tumorigenesis and as a prognostic marker of gastric cancer." (PMID 23985992, 2013). "Further study of galectin-7 regulation may lead to improved gastric cancer diagnosis and therapy." (PMID 23985992, 2013). "The overexpression of galectin-7 in AGS gastric adenocarcinoma cells suppressed cell proliferation, migration, and invasion, whereas the removal of galectin-7 in KATO III gastric carcinoma cells reversed these properties." (PMID 34827718, 2021).
gastric cancer (continued). "Over-expression of galectin-7 in AGS gastric adenocarcinoma cells suppressed cell proliferation, migration, and invasion, whereas ablation of galectin-7 in KATO III gastric carcinoma cells reversed these properties." (PMID 23985992, 2013). "We also found that the Tid1-galectin-7-MMP-9 axis might be one of the malignant regulatory mechanisms for gastric cancer metastasis and provide a potential target for gastric cancer treatment." (PMID 33233689, 2020). "Our results revealed that the galectin-7-MMP-9 pathway might be a regulatory mechanism for the Tid1 knockdown-increased cell migration and invasion of gastric cancer cells." (PMID 33233689, 2020). "Galectin-7 over-expression inhibited cell proliferation as measured by crystal violet staining and WST assay, and significantly decreased gastric cancer cell migration and invasion." (PMID 23985992, 2013). "Quantitative analysis of galectin-7 staining confirmed that gastric cancer patients had low or no expression in malignant tissues compared with normal tissues." (PMID 23985992, 2013). "Galectin-7 mRNA expression was greatly increased in five cell lines, AGS, YCC-2, SNU-1, SNU-601 and SNU-638, following 5-aza-dC treatment, suggesting that DNA methylation suppresses galectin-7 gene expression in these gastric cancer cell lines." (PMID 23985992, 2013). "Moreover, the role of galectin-7 in gastric cancer has not been studied." (PMID 23985992, 2013).
squamous cell carcinoma (6 papers, 2010 to 2026). A carcinoma arising from squamous epithelial cells. "Functional assays were performed in squamous carcinoma cell lines to assess the role of Galectin-7, a transcriptional target of p63, in cellular proliferation." (PMID 41917522, 2026). "An ELISA kit was used to detect the secretion level of Galectin-7 in the plasma of lung cancer patients (Adenocarcinoma (n=20) vs. Squamous cell carcinoma (n=16))." (PMID 40718829, 2025). "In this study, the expression of galectin-7 was investigated in patients with non-small cell (adenocarcinoma (AC) and squamous cell carcinoma (SQCLC)) and SCLC in relation to clinicopathological characteristics and overall survival." (PMID 39465762, 2024). "In lung cancer, squamous cell carcinoma, galectin-7 was also identified as a factor promoting metastasis." (PMID 39465762, 2024). "In squamous cell carcinoma, the expression of galectin-7 has been shown to be induced during tumorigenesis, particularly in the microenvironment of immunosuppression." (PMID 39465762, 2024). "In a mouse model of lung cancer with squamous cell carcinoma cells, galectin-7 was shown to be a key mediator of metastasis in conjunction with immunosuppression." (PMID 39465762, 2024). "We measured significantly higher levels of Galectin-7 in plasma from squamous cell carcinoma patients than in plasma from adenocarcinoma patients, suggesting that it could serve as a biomarker for LUSC (P < 0.0001)." (PMID 40718829, 2025). "In a syngeneic mouse squamous cell carcinoma (SCC) model, Galectin-7 has been recognized as a mediator of metastasis linked to immunosuppression, exhibiting significant induction in the tumor microenvironment during tumorigenesis, and is released extracellularly at advanced stages of tumor growth." (PMID 40718829, 2025). "Not only galectin-3 can be used as a marker in squamous cell carcinomas, expression of galectin-7 seems to be significantly reduced in malignant cells of squamous epithelia of both ectodermal and endodermal origin, thus allowing use of galectin-7 as differentiation marker of epithelial malignancies." (PMID 23658855, 2010). "RNAseq data analysis from a cohort of NMSC patients (E-MTAB-5678 dataset) revealed increased LGALS7 expression in neoplastic (intraepidermal carcinoma; IEC and squamous cell carcinoma; SCC) and pre-neoplastic (actinic keratosis; AK) lesions compared to normal tissue." (PMID 36693903, 2023).
neuroblastoma (5 papers, 2013 to 2024). Neuroblastoma (NB) is the most common solid, extracranial childhood tumor. "Galectin-7 acts similarly to galectin-1 in reducing the growth of neuroblastoma cells, without involving classical apoptosis, thereby playing a key role in spontaneous regression of neuroblastoma." (PMID 35677161, 2022).
colon carcinoma (4 papers, 2010 to 2024). "These new coming results reinforce the rationale of using galectin-7 on tumour that would benefit from its induced expression, as for example colon cancer." (PMID 29257082, 2017). "On the contrary, in colon cancer, galectin-7 ectopic overexpression prevented metastatic dissemination and promoted apoptosis after apoptosis induction by stimuli." (PMID 29257082, 2017). "In a model of human colon carcinoma, for instance, the exogenous expression of galectin-7 aids in eliminating tumor cells through its pro-apoptotic function." (PMID 23658821, 2013). "Indeed, ectopic expression or addition of exogenous galectin-7 in the DLD-1 human colon carcinoma cell line and the neuroblastoma cells SK-N-MC, respectively, drastically reduced tumour cell proliferation." (PMID 29257082, 2017).
lung carcinoma (4 papers, 2014 to 2025). "In this study, we investigated the expression of galectin-7 in relation to clinicopathological features and overall survival in patients with different types of lung cancer." (PMID 39465762, 2024). "We found that galectin-7 is significantly elevated in lung cancer patients with a squamous cell histology." (PMID 34638303, 2021). "Galectin-7 was statistically significantly lower in the first stage of lung cancer than the rest of the stages." (PMID 34638303, 2021). "All these findings show that galectin-1, galectin-3, and galectin-8 are the most abundantly expressed galectins while the expression of galectin-4, galectin-7, and galectin-9 is relatively low, both in tumor tissues and in different lung cancer cell lines." (PMID 25259711, 2014). "Further testing is needed to confirm whether galectin-7 levels could be a differentiating factor for identifying lung cancer tumor types." (PMID 34638303, 2021). "Additionally, our study shows that galectin-7 is elevated in lung cancer patients with a squamous cell tumor histology." (PMID 34638303, 2021).
prostate carcinoma (4 papers, 2015 to 2021). A carcinoma that arises from epithelial cells of the prostate gland. "Galectin-7 is found to be downregulated in prostate cancer cells, and the expression of galectin-7 in prostate cancer cells increases their sensitivity to apoptosis in response to chemotherapeutic agents." (PMID 34827718, 2021). "In vivo, galectin-7 overexpression in prostate cancer cells led to a significant reduction in tumor size, while its CRD-defective mutant form significantly increased tumor growth." (PMID 34827718, 2021). "In contrast, galectin-7 reduces the invasive behaviors of prostate cancer cells by inhibiting their motility." (PMID 34827718, 2021). "It is important to note that we cannot not use the PC3 cells (another classical cell model of human prostate cancer) because these cells express low but significant endogenous galectin-7." (PMID 26168167, 2015). "Collectively, these data demonstrate that KLF5 overexpression regulates ERBB2 expression in AR-positive prostate cancer cells and more broadly regulates ERBB2-related genes LGALS7 and FAM129B in prostate cancer cells regardless of cellular AR status." (PMID 34737261, 2021).
thyroid cancer (4 papers, 2010 to 2024). "It is reported that well-differentiated thyroid carcinomas almost invariably express galectin-3 and galectin-7, while benign thyroid proliferations do not, so expression of galectin-3 and galectin-7 in thyroid malignancy may be as potential diagnostic indicators." (PMID 29951528, 2018).
bladder cancer (3 papers, 2014 to 2025). "As described in the previous section, galectin-7 modulates chemosensitivity of bladder cancer cells to cisplatin." (PMID 40252176, 2025). "Matsui and co-workers showed that bladder cancer cells expressing upregulated galectin-7 tended to respond more sensitively to chemotherapy, compared to urothelial tumor cells having lower levels of galectin-7." (PMID 34827718, 2021). "Galectin-7 has been identified as a potential predictive marker for cisplatin (cis-diamminedichloroplatinum, CDDP) chemosensitivity in bladder cancer." (PMID 40252176, 2025).
endometrial cancer (3 papers, 2020 to 2021). Primary or metastatic malignant neoplasm involving the endometrium (mucous membrane that lines the endometrial cavity). "The latest study suggests that elevated galectin-7 concentrations can promote the development of endometrial cancer via increased cell migration and decreased cell attachment." (PMID 33799622, 2021). "The conclusions drawn by the authors are that galectin 7 have possible influence on the formation of distant metastases in endometrial cancer." (PMID 32859099, 2020). "The role of galectin-7 in endometrial cancer is the subject of research." (PMID 33799622, 2021). "It was demonstrated by Menkhorst and colleagues that galectin-7 production increased in endometrial cancer with increasing cancer grade; galectin-7 may promote the metastasis of endometrial cancer by reducing cell–cell adhesion and enhancing cell migration." (PMID 34827718, 2021).
esophageal squamous cell carcinoma (3 papers, 2010 to 2024). Esophageal squamous cell carcinoma (ESCC) is a type of esophageal carcinoma (EC) that can affect any part of the esophagus, but is usually located in the upper or middle third. "Galectin-7 was reported to be highly expressed in ESCC (esophageal squamous cell carcinoma) during a study that was designed to isolate and identify ESCC biomarkers, using proteomic tools." (PMID 34827718, 2021).
Hypertension (3 papers, 2021 to 2024). The presence of chronic increased pressure in the systemic arterial system. "In this work, people of 50 years of age and older who carried certain LGALS7 alleles were found to be at increased risk for ICH, especially those with hypertension and diabetes (p < 0⋅0001)." (PMID 35401111, 2022). "Previous studies highlight the role of galectin-7 in hypertensive disorders, but clinical data from this study population lack information on co-existing pregnancy-related and non-pregnancy-related conditions, which could also contribute to the upregulation of galectin-7." (PMID 39337670, 2024).
oral squamous cell carcinoma (3 papers, 2014 to 2025). "Consistence with reports in breast, ovarian and oral squamous cell carcinoma, elevated galectin-7 expression acted as a reverse predictive factor in non-metastasis ccRCC patients." (PMID 27259255, 2016).
squamous cell lung carcinoma (3 papers, 2021 to 2025). A carcinoma arising from squamous bronchial epithelial cells. "Conversely, Galectin-7, significantly upregulated in lung squamous cell carcinoma (LUSC) versus LUAD, is validated by increased serum levels and higher immunohistochemistry (IHC) expression in LUSC, indicating its potential as a biomarker." (PMID 40718829, 2025). "Immunohistochemical detection of galectin-7 expression was most evident in squamous cell lung carcinoma (36.27%), followed by adenocarcinoma (5.55%)." (PMID 39465762, 2024). "Within the adenocarcinoma and squamous cell lung carcinoma subgroups, there were statistically significant correlations between the expression of galectin-7 and some clinicopathologic features of the patients." (PMID 39465762, 2024). "There was an intriguing finding that galectin-7 was elevated in serum samples from squamous cell lung cancer patients relative to healthy controls and adenocarcinoma lung cancer patients." (PMID 34638303, 2021). "Galectin-7 expression in squamous cell lung carcinoma sorted by clinical features." (PMID 39465762, 2024).
colorectal cancer (2 papers, 2024 to 2025). A primary or metastatic malignant neoplasm that affects the colon or rectum. "Recently, galectin 7 has been reported to convert the tumor immune environment of colorectal cancer with microsatellite instability and improve responsiveness to anti-PD-1 therapy." (PMID 38503797, 2024).
skin cancer (2 papers, 2013 to 2017). "In skin cancer, a recent study has shown that galectin-7 is induced during neoplastic transformation of the skin following exposure to cypermethrin, a highly carcinogenic insecticide used for agricultural and domestic applications." (PMID 23658821, 2013).
urothelial carcinoma (2 papers, 2014 to 2026). A malignant neoplasm derived from the transitional epithelium of the urinary tract (urinary bladder, ureter, urethra, or renal pelvis). "SP600125 has different apoptotic effects depending on differences in the level of galectin-7 between urothelial carcinomas and normal urothelium." (PMID 24603862, 2014).
adenoma (1 paper, 2021). A neoplasm arising from the epithelium. "Analysis of the expression of galectin-7 in benign and malignant thyroid cancers showed a downregulation of galectin-7 in adenomas, compared to carcinomas." (PMID 34827718, 2021).
asthma (1 paper, 2021). "As galectin-7 was identified to be overexpressed and increased apoptosis occurred in bronchial epithelial cells in asthma, Sun and Zhang investigated the effect of galectin-7 on the apoptosis of human bronchial epithelial cells." (PMID 34827718, 2021).
atopic dermatitis (1 paper, 2018). "Hence, it is not surprising that, in the stratum corneum, galectin-7 is highly expressed in atopic dermatitis patients and possible treatment of this and other skin diseases could target galectin-7." (PMID 29950926, 2018).
clear-cell renal cell carcinoma (1 paper, 2016). "The aim was to appraise Galectin-7 expression on the overall survival (OS) of patients with non-metastatic clear cell renal cell carcinoma (ccRCC) following surgery." (PMID 27259255, 2016).
dry eye (1 paper, 2022). "Similarly, galectin 7 and cytoplasmic 1 were reduced in dry eye and MGD compared with healthy controls but significantly worse in patients with MGD." (PMID 35685417, 2022).
esophageal cancer (1 paper, 2024). A primary or metastatic malignant neoplasm involving the esophagus. "Immunohistochemical staining of samples from esophageal cancer patients showed that galectin 7 expression level was negatively correlated with the percentage of CD4+ T cells." (PMID 38503797, 2024). "Immunohistochemical staining of esophageal cancer patient samples showed a lower percentage of CD4+ cells in the galectin 7 high area." (PMID 38503797, 2024). "Immunohistochemical staining of esophageal cancer patient samples also showed a negative correlation between galectin 7 expression and the percentage of CD4+ T cells." (PMID 38503797, 2024).
gastric tumors (1 paper, 2013). "Although tumors were formed from AGS cells expressing vector control pcDNA 3.0, the galectin-7 over-expressing AGS cells could not form gastric tumors in the xenografted mice." (PMID 23985992, 2013). "AGS cells that overexpressed galectin-7 could not form gastric tumors in xenografted mice." (PMID 23985992, 2013).